XIAP (X-linked inhibitor of apoptosis)
Diseases named in the same sentence as XIAP in open-access papers (continued):
Sharing a sentence is not in itself a finding about the gene and the disease.
glioma (34 papers, 2008 to 2025). A benign or malignant brain and spinal cord tumor that arises from glial cells (astrocytes, oligodendrocytes, ependymal cells). "UC-MSCs can inhibit migration by the upregulation of PTEN and induce apoptosis of glioma cells by the downregulation of X-linked inhibitor of apoptosis (XIAP)." (PMID 30143053, 2018). "Kaempferol-mediated downregulation of ERK phosphorylation in glioma cells decreases the expression of anti-apoptotic proteins survivin and X-linked inhibitor of apoptosis protein, ultimately inducing cell death." (PMID 27109240, 2016). "Additionally, it was reported that human umbilical cord blood-derived MSCs can induce the apoptosis of xenograft cells and glioma cells through downregulation of the X-linked inhibitor of apoptosis protein (XIAP) by activating caspase 3 and caspase-9." (PMID 33472580, 2021). "Despite XIAP and BCL-2 being anti-apoptotic, blocking them is linked to increased apoptosis and reduced glioma survival." (PMID 40739397, 2025). "For instance, miR-185 specifically binds to XIAP to reduce glioma stability, a process that can be inhibited by CRNDE." (PMID 35992856, 2022). "Enforced levels of exogenous miR-7 in TRAIL-overexpressed MSCs sensitize the treatment of TRAIL to increase apoptosis in the death receptor pathway through targeting XIAP in glioma cells." (PMID 35136028, 2022). "Dysregulation of XIAP has been found in several malignancies, including thyroid carcinoma, lymphoma, and glioma." (PMID 35572727, 2022). "The X-linked inhibitor of apoptosis protein (XIAP) and its co-chaperone C-terminus of Hsc70-interacting protein (CHIP) play diverse roles in cancers, including glioma where increased expression promotes low- to high-grade transition." (PMID 32984016, 2020). "This drug has been known to induce down-regulation of anti-apoptotic proteins Bcl-2 and XIAP and up-regulates the expression of pro-apoptotic protein Bax and caspase-3 in glioma cells." (PMID 33396819, 2020). "Embelin is a potent dual inhibitor of 5-lipoxigenase (5-LOX) and microsomal prostaglandin E2 synthase (mPGES)-1 that suppresses proliferation of human glioma cells and induces apoptosis by inhibiting XIAP and NF-κB signaling pathway." (PMID 27770821, 2016). "In this study, we aimed at investigating the expression levels of CRNDE and miR-186 in glioma stem cells and the effects of CRNDE on miR-186-induced regulation of XIAP and PAK7 as well as the underlying mechanism in the process." (PMID 26231038, 2015). "Taken together these data suggests that EDL-360 has a potential therapeutic application for treating glioma, especially when combined with XIAP inhibitors." (PMID 25574358, 2014). "To explore the mechanism of MSC-induced cell death of glioma cells, we did quantitative real-time PCR for caspases 3 and 9, survivin, and XIAP." (PMID 24971310, 2014). "XIAP (X-linked inhibitor of apoptosis, a class of anti-apoptotic proteins), and PAK7 (also known as PAK5, an evolutionarily conserved serine/threonine protein kinase), were highly expressed in glioma cells." (PMID 32195180, 2020). "Furthermore, αB-crystallin expressed in glioma cells incapacitates the anti-apoptotic activity exerted by XIAP." (PMID 27851782, 2016). "Silencing of XIAP promotes apoptosis and reduces tumorigenecity of glioma." (PMID 25831237, 2015). "Consistent with these researches, induction of apoptosis and autophagy of glioma cells might be attributed to downregulation of XIAP by miR-340." (PMID 25831237, 2015). "Indeed, in vitro targeting of XIAP protein sensitized glioma cells to radiotherapy and induced apoptotic cell death." (PMID 25574358, 2014). "For example, although hypoxic insult results in cytochrome C release from glioma cells, apoptosis inhibition using X‐linked inhibitor of apoptosis protein (XIAP) or caspase inhibitors fails to protect cells from hypoxic cell death (Steinbach, Wolburg, Klumpp, Probst, & Weller, 2003)." (PMID 32323496, 2020).
glioma (continued). "CRNDE was found to decrease the XIAP protein level by negatively regulating miR-186 which specifically binds to the 3′-UTR of XIAP and impairs its stability in glioma stem cells." (PMID 33138314, 2020). "However, sensitivity to PAC-1 in vitro was not identified to be directly proportional to resting PC-3 alone or in the context of XIAP, a known IAP involved in glioma apoptosis resistance." (PMID 30859090, 2019). "And the up-regulation of KNG1 significantly suppressed the expression of XIAP and increased the apoptosis in vivo, suggesting overexpression of KNG1 could promote the apoptosis of glioma cells." (PMID 30068373, 2018). "In summary, XIAP and PAK7 are involved in the important biological processes of glioma cells." (PMID 26231038, 2015). "Since EDL-360 induced the apoptosis of glioma cells and this effect was augmented when EDL-360 treatment was combined with a XIAP inhibitor (embelin), we investigated the effect of the combination treatment with an inhibitor of apoptosis (decylubiquinone, dUb)." (PMID 25574358, 2014). "Since EDL-360 induced apoptosis in glioma cultures, we considered whether simultaneous treatment with EDL-360 and embelin (a XIAP inhibitor) would increase the potency of EDL-360 compound." (PMID 25574358, 2014). "Not surprisingly, overexpression of XIAP has been observed in many cancer types including glioma, leukemia, melanoma and carcinoma." (PMID 25574358, 2014). "However, a study on glioma cells demonstrated no suppression of XIAP protein despite induction of apoptosis, suggesting suppression of other antiapoptotic molecules such as Bcl2 and Bcl-XL in these cells." (PMID 26347311, 2015). "The expression of the potential TRAIL inhibitors XIAP and cFLIP was higher in the TRAIL-sensitive D2247 cells than the resistant lines, arguing against overexpression of these proteins as a mechanism of resistance in gliomas that survived incubation with TRAIL." (PMID 18594532, 2008). "In our study, the expressions of cyclinD1, ki67 and XIAP were obviously reduced by the overexpression of KNG1; while the expressions of caspase-3 and caspase-9 were increased, suggesting the up-regulation of KNG1 could exert pro-apoptotic property in glioma cells." (PMID 30068373, 2018). "However, in glioma cell lines, embelin did not significantly alter XIAP protein levels." (PMID 24603802, 2014). "Knock-down of ROCK1 in glioma cells did not significantly influence EZH2, EGFR, XIAP and BMI1 expression, which indicates miR-340, regulates these oncogenes through distinct mechanisms bypassing ROCK1." (PMID 25831237, 2015).
hepatocellular carcinoma (33 papers, 2009 to 2026). A malignant tumor that arises from hepatocytes. "The overexpression of the X-linked inhibitor of apoptosis (XIAP) protein in hepatocellular carcinoma promotes metastasis and tumor recurrence." (PMID 37434213, 2023). "Patients with XIAP-positive hepatocellular carcinoma tumors showed a higher risk of relapse – in this tumor type XIAP can be defined as a biomarker that promotes metastasis and tumor recurrence." (PMID 25120954, 2014). "The effect of XIAP inhibition in combination with thermal ablation on hepatocellular carcinoma is elusive." (PMID 39917292, 2025). "ES contains XIAP-inhibiting compounds that promote caspase-dependent apoptosis in hepatoma and HSC models." (PMID 41514859, 2025). "XIAP protein expression is significantly increased in recurrent hepatocellular carcinoma tissues of patients who previously received microwave ablation therapy." (PMID 39917292, 2025). "In human prostate and hepatocellular carcinoma cells, the XIAP expression correlates with apoptosis resistance and increased metastatic foci in vivo." (PMID 25120954, 2014). "Therefore, the aim of this study was to evaluate the effect of pharmacological inhibition of XIAP in combination with MMA on hepatocellular carcinoma treatment in vitro and in vivo." (PMID 39917292, 2025). "This study was conducted to investigate the roles of lncRNA PLAC2 and XiaP in hepatocellular carcinoma (HCC)." (PMID 35475470, 2022). "In this study, we found that the XIAP inhibitor AZD5582 modulates the immune microenvironment and inhibits the progression of post-ablation residual hepatocellular carcinoma." (PMID 39917292, 2025). "Thus, there might be a potential therapeutic relevance of targeting SMAC and XIAP together, in a chronic inflammatory and pro-apoptotic disease such as ALD which may also progress to hepatocellular carcinoma, to achieve desired effects." (PMID 34025452, 2021). "In hepatocellular carcinoma XIAP overexpression compared to non-cancerous tissues is equivocal, though XIAP expression correlated with HCC recurrence and patient survival after treatment." (PMID 19397802, 2009).
acute myeloid leukemia (29 papers, 2009 to 2025). Acute myeloid leukemia (AML) is a group of neoplasms arising from precursor cells committed to the myeloid cell-line differentiation. "Therapy response is diminished in AML (acute myeloid leukemia) patients with frequently overexpressed XIAP mRNA and protein levels." (PMID 34712428, 2021). "In contrast to these finding in adult AML, in childhood de novo acute myeloid leukemia the levels of XIAP correlated with an immature FAB-subtype." (PMID 23211188, 2012). "XIAP is ubiquitous in normal tissues, and is elevated in some cancers including renal, acute myeloid leukaemia and bladder cancer." (PMID 19563669, 2009). "Interestingly, it has been found that circ-PAN3 can positively regulate XIAP expression, leading to chemoresistance in acute myeloid leukemia." (PMID 39866238, 2025). "Notably, circ-PAN3 has been shown to positively regulate XIAP, leading to chemoresistance in acute myeloid leukemia." (PMID 39866238, 2025). "Notably, XIAP inhibitors have shown promising outcomes in cancer therapy, including acute myeloid leukemia." (PMID 33023644, 2020). "The prognostic significance of XIAP has been studied in childhood acute myeloid leukemia (AML)." (PMID 24478984, 2014). "On the contrary, patients of acute myeloid leukaemia with low expression level of XIAP could get more favorite prognosis." (PMID 21645409, 2011). "In acute myeloid leukemia (AML), circPAN3/miR-153-5p/miR-183-5p/XIAP axis is reported to mediate drug resistance." (PMID 32122355, 2020). "Furthermore, XIAP is of great importance in the apoptosis resistance of HL-60 cells when co-cultured with BMSCs through direct cell contact, and the inhibition of XIAP provides a new strategy for treating acute myeloid leukemia." (PMID 31660045, 2019). "In the clinic, phase II trials initially reported successful outcome in acute myeloid leukemia (AML) patients undergoing therapy using antisense oligonucleotide AEG35156 that target XIAP." (PMID 28424988, 2017). "A longitudinal study of patients with acute myeloid leukemia (AML) revealed a correlation between poor prognosis and elevated XIAP levels." (PMID 28666324, 2017). "The correlation between elevated XIAP levels and clinical outcome, however, is not straightforward since its overexpression correlates with disease severity in acute myeloid leukaemia but not in lung cancer or prostate cancer." (PMID 19563669, 2009). "Shang’s team identified 49 circRNAs that were differentially expressed in DXR-resistant and sensitive THP-1 acute myeloid leukemia cell lines, and among them, circPAN3 knockdown could sensitize resistant THP-1 cells to DXR through the miR-153-5p/miR-183-5p-XIAP axis." (PMID 33817271, 2020). "This study found that FGNs could treat acute myeloid leukemia subtype 2 (AML-M2) by silencing five essential oncogenes (BAG1, MDM2, Bcl-2, BIRC5, and XIAP) in AML-M2." (PMID 36612296, 2023).
lymphoma (29 papers, 2004 to 2025). A malignant (clonal) proliferation of B- lymphocytes or T- lymphocytes which involves the lymph nodes, bone marrow and/or extranodal sites. "Knockdown of USP9X leads to suppressed lymphoma growth and increased sensitivity to chemotherapy by destabilizing X-linked inhibitor of apoptosis protein (XIAP) in B-cell lymphoma, independently of Mcl-1." (PMID 34454635, 2021). "Nevertheless, 0 of the 12 XIAP-deficient patients developed lymphoma, consistent with previous reports." (PMID 31754776, 2020). "ASTX660, a non-peptidomimetic small molecule antagonist of cIAP1/2 and XIAP (X-linked inhibitor of apoptosis protein), is in phase 1/2 study for advanced solid tumors and lymphomas and phase 2 study for Peripheral and Cutaneous T-Cell Lymphoma (TCL)." (PMID 32708302, 2020). "Originally, the function ascribed to XIAP was anti-apoptotic activity; hence, loss of XIAP protein may protect patients from lymphoma." (PMID 31754776, 2020). "The IAP family member XIAP, and inherited loss of XIAP, has been implication in X-linked lymphoproliferative type 2 disorder (XLP2), which manifests with lymphohystiocytosis, hypogammaglobulinemia, and lymphomas." (PMID 33432113, 2021). "In summary, our present work demonstrated a novel pathway related to lysosomal ceramide, CTSB, and XIAP in IL-2(−)-induced NK/T lymphoma cell apoptosis." (PMID 25855965, 2015). "The pathophysiological implication of this lysosomal ceramide/CTSB/XIAP axis in apoptotic cell death should be clarified in the future to develop a targeting therapy for NK/T lymphoma." (PMID 25855965, 2015). "Studies in B-cell receptor (BcR-) activated lymphoma cells have shown that de novo Cer formation induces degradation of XIAP in a proteasome-dependent manner." (PMID 23091403, 2012). "Alternatively, the level of XIAP and/or cIAP2 in mutant lymphomas may recalibrate the threshold of caspase activity that a cancer cell can withstand before committing to irreversible apoptosis cascade." (PMID 37679334, 2023). "Among SAP-deficient patients, 2 of 13 (15.4%) developed EBV-positive Burkitt lymphoma, while no XIAP-deficient patient presented with lymphoma." (PMID 31754776, 2020). "Approximately 30% of SAP-deficient patients are reported to develop lymphoma; however, no XIAP-deficient patients with lymphoma have been reported to date." (PMID 31754776, 2020). "Thus we examined the expression level of c-Myc, and Bcl-2 family proteins such as Mcl-1, Bcl-xl and xIAP, which provide aberrant survival advantage for lymphoma cells, in OCI-LY3 EXOs and its parental cell line." (PMID 30103789, 2018). "Moreover, knockdown of USP9X or XIAP significantly delays lymphoma development and increases sensitivity to spindle poisons in a murine Eμ‐Myc lymphoma model." (PMID 27317434, 2016). "However, how ASM-generated lysosomal ceramide is related to the cathepsin family, including CTSB and CTSD and XIAP in NK/T lymphoma cell apoptosis, is poorly understood." (PMID 25855965, 2015). "None of the seven XIAP-deficient patients had colitis or lymphoma." (PMID 31754776, 2020). "Finally, we investigated whether exogenous C2-ceramide mimics IL-2(−)-mediated CTSB activation, XIAP degradation, and caspase-dependent NK/T lymphoma cell apoptosis." (PMID 25855965, 2015). "In the present study, we found that the relative mRNA expression and protein levels of XIAP in ALL cells, KOPN-8, EU-4, NALM-6, EU-6 and SEM were significantly higher than those in human lymphoma cells H9." (PMID 32062612, 2020). "XIAP-deficient patients also never experience lymphoma in contrast to patients with SAP deficiency, likely related to the anti-apoptotic function of XIAP, which may protect patients from cancer, and XIAP is now considered as a promising therapeutic target for cancer treatment." (PMID 29942301, 2018).
lymphoma (continued). "XLP2 caused by mutation in XIAP shares the susceptibility to EBV with a high risk of HLH, but no patient with lymphoma has so far been reported." (PMID 23818254, 2013). "In the absence of TRAF3, this NF-κB2/XIAP/cIAP2 signaling cascade may constitute an autoregulatory positive feedback loop and TRAF3-mutant lymphoma cells may rely on this feedback mechanism for their survival." (PMID 37679334, 2023).